IL18 (interleukin 18)
Diseases named in the same sentence as IL18 in open-access papers (continued):
Sharing a sentence is not in itself a finding about the gene and the disease.
pneumonia (31 papers, 2013 to 2025). An acute, acute and chronic, or chronic inflammation focally or diffusely affecting the lung parenchyma, caused by an infection in one or both of the lungs (by bacteria, viruses, fungi, or mycoplasma.). "IL-18 produced by AMs protects against pneumonia and ALI associated with S. pneumoniae infection via enhancing the bacterial clearance." (PMID 32849610, 2020). "However, IL-18 proves detrimental to P. aeruginosa-induced pneumonia and enhances its invasiveness to cause sepsis and ALI." (PMID 32849610, 2020). "The treatment of these aged mice with inflammasome activators [Nigericin, which promotes potassium (K+) efflux increases the synthesis and release of inflammasome activation-dependent cytokines (IL-1β and IL-18)] increase their survival and decreases their susceptibility toward pneumonia and ALI." (PMID 32849610, 2020). "Additionally, we observed that the presence of the IL18-rs1834481 polymorphism was an independent risk factor for developing pneumonia, also displaying a 1.7-fold increased risk for more severe disease; although the latter was not marginally reached to statistical significance." (PMID 37766191, 2023). "Elevated IL-1β and IL-18 levels were found in the brains of mice with L. pneumophila-induced pneumonia." (PMID 39816309, 2024). "First, patients with HIV and pneumonia exhibited elevated plasma levels of various cytokines, including IL-6, IL-8, IL-18, IL-1RA, IL-10, IP-10, MCP-1, and MIP-1β, compared to patients with HIV alone." (PMID 38251391, 2024). "Patients with HIV and pneumonia presented elevated levels of cytokines and chemokines (IL-6, IL-8, IL-18, IL-1RA, IL-10, IP-10, MCP-1, and MIP-1β) compared to those with only HIV." (PMID 38251391, 2024). "In this study, we selected an appropriate cytokine, IL-18, based on the special cytokine expression profile in severe pneumonia of mice induced by H1N1virus to prime hUC-MSCs in vitro and improve the therapeutic effect of hUC-MSCs in vivo." (PMID 36707501, 2023). "In this study, IL-18 first showed higher expression in a mouse model of severe pneumonia, and IL-18 was used for priming hUC-MSCs in vitro." (PMID 36707501, 2023). "In pneumonia, for instance, IL-1β and IL-18 can activate inflammatory cells, such as macrophages to release inflammatory mediators, causing inflammatory responses characterized by infiltration of macrophages and granulocytes in the lung." (PMID 36233009, 2022). "A multiplex-biometric immunoassay showed that pneumonia cases had higher levels of serum cytokines (G-CSF, IL-2, IL-6, IL-10, IL-18, IP-10, MCP-3, and TNF-α) than bronchitis cases." (PMID 36119044, 2022). "Results using a murine model of pneumonia indicate that IL-1β and IL-18 participate in the suppression of host capabilities to clear P. aeruginosa pulmonary infection." (PMID 34572625, 2021). "Besides, another study also explored the immune reactions in Chlamydia psittaci pneumonia and they found psittacosis cases with pneumonia had higher levels of serum cytokines (G-CSF, IL-2, IL-6, IL-10, IL-18, IP-10, MCP-3, and TNF-α) than bronchitis cases." (PMID 40236451, 2025). "In our study, patients with HIV and pneumonia exhibit immune dysregulation, characterized by elevated levels of proinflammatory cytokines (IL-6, IL-8, IL-18), anti-inflammatory cytokines (IL-1RA, IL-10), and chemokines (IP10, MCP-1, MIP-1β) in their plasma, compared to the HIV group." (PMID 38251391, 2024). "Moreover, LAA treatment reduced ASC, pro-caspase-1, caspase-1 p20, pro-IL-1β, mature-IL-1β, and IL-18 activation in the lungs of pneumonia mice in comparison with S. aureus-treated mice." (PMID 38803378, 2024). "Collectively, IL-18 is an important cytokine in the proinflammatory microenvironment of influenza virus-induced severe pneumonia and could influence MSC priming in vitro and in vivo." (PMID 36707501, 2023). "Together, they demonstrated that IL-18 could be important in cases of H1N1-induced severe pneumonia." (PMID 36707501, 2023).
pneumonia (continued). "Moreover, IL-18 is more elevated in patients with most severe pneumonia and worse outcomes." (PMID 36287942, 2022). "Increased IL-18 levels have been observed in patients with HIV and pneumonia, suggesting an exacerbated inflammatory response." (PMID 38251391, 2024). "Elevated concentrations of both pro- and anti-inflammatory plasma cytokines were observed in the pneumonia group, including G-CSF, HGF, IL-1b, IL-1RA, IL-2, IL-2Ra, IL-6, IL-10, IL-18, IP-10, monocyte chemoattractant protein-3 (MCP-3), and TNF-α." (PMID 36119044, 2022). "For example, potentially useful biomarkers for severe or refractory pneumonia include AST, ALT, LDH, CRP, ferritin, and various cytokines (IL-18, IL-6, or TNF-α)." (PMID 33810090, 2021). "Another study also found a correlation between lower IL-18 and IFN-γ common in RSV infection and worse Spn pneumonia." (PMID 33705390, 2021). "Suppression of gene expression of IL-18 receptor accessory protein might contribute to reduction of pneumonia in RSV-infected offspring mice treated with methamidophos, because IL-18 is an inducer of IFN-γ." (PMID 24369005, 2013). "Unlike MEDI4893*, which protected 100% of the mice from lethal pneumonia, neutralization of the individual cytokines, IL-1 or IL-18, alone or in combination did not significantly affect survival during a lethal infection or bacterial clearance in a sublethal infection." (PMID 29490278, 2018). "Further sample collection, including plasma, pleural effusion, and BALF, is necessary to evaluate the predictive value of IL-18, the IL-18/IL-38 ratio, and IL-33 for PPE and to determine whether respiratory colonization by Hi can attenuate inflammatory cytokine production during pneumonia." (PMID 40352606, 2025).
malaria (30 papers, 2012 to 2025). Malaria is a serious and sometimes fatal disease caused by a parasite that commonly infects a certain type of mosquito which feeds on humans. "Whereas IL-18 may have protective effects in various models of experimental malaria, high levels of IL-18 have been associated with disease severity in clinical P. falciparum infection." (PMID 34663245, 2021). "Moreover, a study in Papua New Guinea, suggests that IL-18 decrease the risk of clinical malaria in children through a modulatory effect on T cells." (PMID 34663245, 2021). "Additionally, the possible role of the IL18 gene variants rs187238 and rs1946518 in severe malaria anemia and mortality were also investigated in a Kenyan children population." (PMID 27027876, 2016). "In field studies, plasma IL-18 levels increase during uncomplicated and severe clinical malaria cases and remain elevated at follow-up51." (PMID 38890271, 2024). "HBB and IL18 were enriched in African trypanosomiasis and malaria, respectively, and they were also involved in oxygen transport and the adaptive immune response, as identified in the GO analysis." (PMID 37958518, 2023). "Increased IFN-γ, CXCL10, CX3CL1, IL-18, and IL-27 levels were observed in malaria coinfections compared to HIV monoinfection." (PMID 36716305, 2023). "Immune-related genes TLR2 in Malaria and Legionellosis and IL-18 and IL18R1 in the TNF signaling pathway were upregulated in the LG compared to in the BG (p < 0.05)." (PMID 35268235, 2022). "TLR2 in Malaria and Legionellosis and IL-18 and IL18R1 in the TNF signaling pathway were upregulated in the LG compared to in the BG (p < 0.05)." (PMID 35268235, 2022). "Given that IL-18 is an early cytokine/alarmin in malaria and has been shown to activate basophils, we sought to determine the role of the basophil IL-18R in this protective phenotype." (PMID 35985797, 2022). "(i) IL-18 and IL-18bp were markedly up-regulated during falciparum malaria with particular high levels in malaria patients co-infected with HIV and severe malaria disease." (PMID 34663245, 2021). "(ii) In the malaria group as a whole, both IL-18 and IL-18bp were positively correlated with disease severity, parasitemia, and endothelial cell activation as assessed by vWF in plasma." (PMID 34663245, 2021). "Further, the IL-18pb levels declined and thereby contributed to an increase in IL-18/IL-18bp ratio in all subgroups of malaria patients." (PMID 34663245, 2021). "Previous publications have described IL18 as a major player in the pathogenesis of severe malaria through a pathway of elevating IFN-gamma." (PMID 34565410, 2021). "Addition of recombinant IL-18 revealed significant synergy between IL-18 and malaria immune serum for IFN-γ production and degranulation responses whereas only limited additive effects were observed in the presence of antibody depleted serum." (PMID 32296438, 2020). "We cultured PBMC from Gambian or UK subjects in the presence of malaria immune serum and with neutralizing antibodies against IL-12, IL-18, or isotype control antibodies." (PMID 32296438, 2020). "Here, we investigated the effects of modulating IL-18 release and production on the histopathological changes during malaria infection, with the ultimate aim of evaluating the significance of IL-18 role in malaria pathogenesis." (PMID 26622294, 2015). "In this study, we demonstrated the effect of modulating IL-18 on the histopathological conditions of malaria infected mice." (PMID 26622294, 2015). "In this model of malaria, all the inflammatory cytokines (TNFα, IFNγ, IL-1, IL-6, IL-18, IL-10) were found to be significantly elevated in the systemic circulation." (PMID 23323093, 2012). "IL-18 was found to be highly elevated in this model of malaria, especially during the late critical stages of the infection." (PMID 23323093, 2012). "Among severe malaria cases, IL-18 tended to remain high throughout the course of the disease." (PMID 38404582, 2024).
malaria (continued). "Moreover, Singh and colleagues demonstrated that IL-18 plays a protective role in host defense by enhancing IFN-γ production during murine malaria blood-stage infection." (PMID 38787228, 2024). "Furthermore, a noteworthy correlation was found between the level of IL-18 in severe malaria patients and the degree of parasitaemia." (PMID 38404582, 2024). "The IL-18 system is integral to the pathogenesis of P. falciparum, with both IL-18- and IL-18-binding proteins correlating positively with disease severity, parasitemia and endothelial cell activation in the plasma of malaria patients." (PMID 39548522, 2024). "IL‐18 induces severe malaria through an elevating IFN‐γ pathway." (PMID 38099246, 2023). "Several inflammatory mediators participate in the host response to malaria, and in the present study we show a marked regulation of IL-18 and its binding protein IL-18bp during falciparum malaria, with particular high levels in patients with severe malaria disease that were co-infected with HIV." (PMID 34663245, 2021). "Interestingly, plasma levels of IL-18bp showed a similar pattern as IL-18 with a marked increase in all the three patient groups compared to healthy controls with the highest levels in the malaria patients co-infected with HIV and severe disease." (PMID 34663245, 2021). "Indeed, during follow-up there was a rise in IL-18/IL-18bp ratio in all subgroups of malaria patients." (PMID 34663245, 2021). "Based on studies in experimental malaria it has been suggested that IL-18 could have a protective effect in the infected host, at least partly related to its effect on NK cells." (PMID 34663245, 2021). "In addition, levels of IL-23 were higher in the peripheral blood of Kenyan children with malaria anemia, whilst IL-18 promoter haplotypes that result in elevated IL-18 expression during acute infection have been associated with increased risk of SMA." (PMID 32373101, 2020). "In cases with severe malaria, IL-18 tended to be high during the disease course." (PMID 30717382, 2019). "In addition, there was a significant correlation between the IL-18 level in severe malaria patients and the extent of parasitemia." (PMID 30717382, 2019). "For histopathological examination on treatment with IL-18 related drugs, the malaria-infected mice were treated with PBS, rmIL-18 Fc chimera, and rmIL-18 respectively for four days and were sacrificed for organ collection on day 5 post inoculations and treatment." (PMID 26622294, 2015). "Another study from the same team discovered that IL-18 and IL-18 binding protein (IL-18 bp) were significantly upregulated during malaria, with the highest levels in malaria patients co-infected with HIV and experiencing severe malaria." (PMID 40950582, 2025). "All three of these cytokines are increased during human malaria, while IFN-γ and IL-18 are increased during canine babesiosis." (PMID 36839438, 2023). "Distinct cytokine profiles in malaria and HIV coinfections compared to malaria monoinfections were increased IL-12, CXCL9, CXCL11, IL-18, and G-CSF levels and decreased TNF and IL-4 levels." (PMID 36716305, 2023). "The interactions between pro- and anti-inflammatory cytokines such as IL-12, IL-18 and TGF-β have been shown to play a key role in malaria pathogenesis and outcome, whereby they modulate the immune response against Plasmodium falciparum, which causes malaria." (PMID 36501067, 2022). "We have recently shown increased IL-27 levels in this cohort of malaria patients potentially mediating both inflammatory and anti-inflammatory effects and our data in the present study suggest that IL-27 could balance the activity of the IL-18 system by increasing the level of IL-18bp." (PMID 34663245, 2021). "In the present study that included 131 patients with falciparum malaria, we found markedly raised levels of IL-18 in these patients compared with healthy controls with the highest levels in those co-infected with HIV and severe malaria disease." (PMID 34663245, 2021).
malaria (continued). "When comparing malaria patients based on the severity of their condition- non-complicated, severe, and cerebral malaria - increased IL-18 levels were observed across all three groups." (PMID 38404582, 2024). "This pattern seemed primarily to reflect a decrease in IL-18bp in all sub-groups of patients, whereas IL-18 did not change in patients with malaria and HIV but actually increased in patients with malaria only." (PMID 34663245, 2021). "In contrast, blockade of neither IL-18 nor IL-12 significantly reduced the frequencies of IFN-γ or CD107a expressing total CD56dim NK cells responding to iRBC in the presence of malaria immune serum in Gambian subjects." (PMID 32296438, 2020). "Since IL-12 and IL-18 levels are increased in malaria-infected individuals and promote IFN-γ release from NK and T cells, we investigated whether PfEMP1 modulated IL-12 and IL-18 release." (PMID 29038124, 2018). "Indeed, malaria patients without HIV had similar IL-18 level as HIV-infected patients with similar febrile symptoms but without falciparum infection, illustrating the “inflammatory” contribution of HIV." (PMID 34663245, 2021). "Moreover, during follow-up all malaria patients showed an increase in IL-18/IL-18bp ratio, irrespective of disease severity and co-infection with HIV primarily reflecting a decline in IL-18bp, suggesting a net inflammatory temporal effect in the IL-18 system." (PMID 34663245, 2021). "Furthermore, IL-12 and IL-18 synergistically could increase the IFN-γ production by macrophages, T cells, and NK cells, indicating that IL-12 plays a role in cell-mediated immune response in malaria." (PMID 35954703, 2022). "(iii) Whereas there was no change in IL-18 levels in malaria patients co-infected with HIV during follow-up, the patients with malaria only had slightly increased IL-18 levels." (PMID 34663245, 2021). "When serum levels of IL-18 and IFN-γ were measured by dividing malaria patients into non-complicated, severe, and cerebral malaria, an increase in IL-18 levels was observed in all three groups." (PMID 30717382, 2019). "Moreover, whereas IL-18 and IL-18bp were significantly correlated in patients with malaria without accompanying HIV infection, this was not seen in malaria patients co-infected with HIV." (PMID 34663245, 2021). "Whereas there were no changes in plasma IL-18, IL-18bp and IL-18/IL-18bp ratio during follow-up in HIV-infected patients without malaria, the malaria patients showed a marked significant increase in IL-18/IL-18bp ratio independent of co-infection with HIV and disease severity." (PMID 34663245, 2021).